SMAD4 (SMAD family member 4)
Diseases named in the same sentence as SMAD4 in open-access papers (continued):
Sharing a sentence is not in itself a finding about the gene and the disease.
pituitary adenomas (1 paper, 2012). "BMP4 is up-modulated in pituitary adenomas in both mice and humans and acts via SMAD4 to up-regulate c-myc, with signalling mechanisms overlapping with the estrogen receptor." (PMID 23226476, 2012).
postmenopausal osteoporosis (1 paper, 2019). Metabolic disorder associated with fractures of the femoral neck, vertebrae, and distal forearm. "First, SMAD4 expression was found to be upregulated in postmenopausal osteoporosis." (PMID 31064048, 2019). "Gene expression profiles suggested that SMAD4, CACNG1, and TRIM63 may have vital roles in the molecular mechanism of postmenopausal osteoporosis and that miR-331 may be a potential biomarker for postmenopausal osteoporosis, however, further studies are required." (PMID 31064048, 2019).
premature ovarian failure (1 paper, 2022). "Knockout of SMAD4 in the ovarian granulosa cells led to the premature luteinization of granulosa cells and eventually premature ovarian failure." (PMID 35739850, 2022).
rectal adenoma (1 paper, 2012). "Array CGH found that copy number increase of GPNMB (7p15.2), OXGR1 (13q32.1), C13orf27 (13q32.2-q34), PMEPA1 (20q13.31), PHACTR3 (20q13.32) and decrease of SMAD4 (18q21.2), BCL2 (18q21.33) occurred in both rectal adenoma and carcinoma." (PMID 23158542, 2012).
sarcopenia (1 paper, 2023). Progressive decline in muscle mass due to aging which results in decreased functional capacity of muscles.
silicosis (1 paper, 2020). Silicosis is a respiratory disease caused by breathing in (inhaling) silica dust. "In this study, we focused on exploring the role of SMAD4 and miR‐34a in mouse silicosis fibrosis and the EMT induced by TGF‐β1 in vitro." (PMID 32929850, 2020). "In addition, no previous study has explored the relationship for SMAD4 and miR‐34a in silicosis." (PMID 32929850, 2020).
Sjögren's syndrome (1 paper, 2016). "We investigated the role of Smad4, a signaling molecule of the TGF-beta pathway, in T cells on the pathology of Sjögren's syndrome (SS) in nonobese diabetic (NOD) mice, an animal model of SS." (PMID 27880731, 2016).
sleep apnoea (1 paper, 2020). "Results suggest that increased levels of SMAD4, mediated by intermittent hypoxaemia and circadian rhythm deregulation, may be associated with cardiometabolic comorbidities in patients with sleep apnoea." (PMID 32722512, 2020).
small intestinal adenocarcinomas (1 paper, 2021). "Also for sporadic small intestinal adenocarcinomas, not included in most large pan-cancer data-sets, SMAD4 has been suggested to have a critical role." (PMID 33509126, 2021).
small-bowel cancer (1 paper, 2021). "In conclusion, TMB levels correlated with tumor prognosis and SMAD4 mutations were associated with recurrence after R0 resection in patients with small-bowel cancer." (PMID 34014970, 2021). "Finally, the RFS of patients with small-bowel cancers containing SMAD4 mutations was significantly poorer than that of patients without SMAD4 mutations." (PMID 34014970, 2021). "Currently, adjuvant chemotherapy is not recommended for all patients with Stage II CRC in Japan; however, these results suggest that postoperative adjuvant chemotherapy should be considered for Stage II small-bowel cancer with SMAD4 mutations because of the high risk of recurrence." (PMID 34014970, 2021). "However, there are currently no reports regarding the significance of SMAD4 variants in patients with small-bowel cancer." (PMID 34014970, 2021).
systemic lupus erythematosus (1 paper, 2020). An autoimmune multi-organ disease typically associated with vasculopathy and autoantibody production. "In the third trimester, systemic lupus erythematosus and proteasome were enriched in the acute disease while Fc gamma R-mediated phagocytosis (VAV1, MARCKSL1, WASF2, DNM2, HCK, MAP2K1 genes) and adherens junction (ACTG1, WASF2, SMAD4, CSNK2B, EP300 genes) represented the subclinical category." (PMID 32012176, 2020).
T-cell lymphoma (1 paper, 2021). "In 2010, associations between T-cell lymphoma and SMAD4 have also been revealed." (PMID 34899868, 2021).
teratocarcinoma (1 paper, 2016). A germ cell tumor characterized by the presence of an embryonal carcinoma component and a teratoma component. "However, BMP signaling enhances Ihh promoter activity and association of Smad4 with SBEs in mouse teratocarcinoma P19 cells." (PMID 27741240, 2016).
tubular carcinomas (1 paper, 2017).
type 1 diabetes (1 paper, 2017). "Therefore, Smad4 deficiency in T cells may affect metabolic pathway and desensitize pathogenic Teff cells, contributing to the promotion of type 1 diabetes." (PMID 27686408, 2017). "As type 1 diabetes is considered to be a T-cell-mediated disease, we analyzed the T cell composition in PLNs from Smad4 tKO and WT NOD mice at 12 weeks of age." (PMID 27686408, 2017). "In summary, our results demonstrate that TGF-β signaling disruption by Smad4 deletion in T cells of NOD mice accelerates the development of type 1 diabetes and increases the incidence of the disease." (PMID 27686408, 2017).
urachal adenocarcinoma (1 paper, 2025). "Among these, SMAD4 mutations show a stronger association with the mucinous subtype of urachal adenocarcinoma compared to other histological types." (PMID 39778497, 2025).
uremia (1 paper, 2013). A clinical syndrome associated with the retention of renal waste products or uremic toxins in the blood. "Smad2 and Smad4, TGFBR2 and other members of the TGF-beta and BMP pathways, among the most highly dysregulated probe sets in uremia, may reflect altered bone metabolism." (PMID 23809614, 2013).
urothelial carcinomas of the renal pelvis (1 paper, 2019). "In a study that comprised 34 urothelial carcinomas of the renal pelvis and ureter Smad4 expression was detected in 17.6% of the cases, which is a smaller percentage than in present study (45.2%)." (PMID 31238579, 2019).
uterine tumors (1 paper, 2023). "We profiled the data from uterine tumors deposited to the cBioPortal of Cancer Genomics for mutations of the TGFβ signaling pathway and identified several mutations in TGFβ-related receptors (TGFBR1, TGFBR2, ACVR1B, ACVR1C, ACVR2A, ACVR2B) and transcription factors (SMAD2, SMAD3, SMAD4)." (PMID 36906706, 2023).
vulvar squamous cell carcinoma (1 paper, 2019). An invasive squamous cell carcinoma arising from the vulva. "In addition, a recent study revealed a common pathway that regulated both MMPs and Smad4 in vulvar squamous cell cancer." (PMID 31777582, 2019).
ZIKV infection (1 paper, 2020). "In vitro, we found that ZIKV infection reduced Foxp3 expression in EL‐4 cells, as well as Smad4 in addition to the reduced phosphorylation of Smad2 and Smad3." (PMID 32057179, 2020). "We showed that overexpression of Smad2 significantly enhanced P‐Smad2 as well as Foxp3 expression level, and ZIKV infection still significantly reduced level of P‐Smad2, P‐Smad3, Smad4 and Foxp3." (PMID 32057179, 2020). "Overexpression of Smad4 exerted no influence on P‐Smad2 and P‐Smad3 expression, but significantly increased Smad4 and Foxp3 expression, ZIKV infection still significantly reduced P‐Smad2, P‐Smad3, Smad4 and Foxp3 expression." (PMID 32057179, 2020). "ZIKV infection did not affect Smad2 and Smad3 expression, but significantly down‐regulated Smad4 expression as well as P‐Smad2 and P‐Smad3 (P < .05)." (PMID 32057179, 2020). "However, compared to ZIKV infection in mock transfection (no Smad2 overexpression), overexpression of Smad2 significantly increased level of Smad3, P‐Smad3, Smad4 and Foxp3." (PMID 32057179, 2020). "However, compared to ZIKV infection in mock transfection (no Smad4 overexpression), overexpression of Smad4 remarkably up‐regulated Smad4 and Foxp3 expression." (PMID 32057179, 2020).
tumor (1,319 papers, 1998 to 2026). "Given previous evidence suggesting that SETD2 loss exacerbates genomic instability and accelerates tumor progression, particularly in SMAD4‐deficient CRC, we further explored the combined prognostic impact of these two genes." (PMID 41562159, 2026). "Among these, SMAD4 mutations, present in >50% of cases, represent a critical transition in tumor progression and are associated with increased invasiveness and poor outcomes, yet their detailed molecular mechanisms remain poorly understood." (PMID 40856537, 2026). "Loss of SETD2 promotes genomic instability and accelerates tumor progression, particularly in the context of SMAD4‐deficient CRC." (PMID 41562159, 2026). "Despite the critical role of SMAD4 in tumor suppression, the molecular mechanisms linking SMAD4 loss to oncogenesis remain poorly understood and cannot be solely attributed to disruptions in canonical TGF-β signaling." (PMID 40856537, 2026). "Consistent with our findings regarding poor survival, SMAD4 alterations have been widely associated with increased tumor aggressiveness and a poly‐metastatic potential in CRC." (PMID 41562159, 2026). "As a tumor‐suppressor gene located on chromosome 18q21, SMAD4 mutations are present in 5.0%–24.2% of CRC cases." (PMID 41562159, 2026). "FoundationOne next-generation sequencing of the tumor showed mutations in NRAS, CTNNB1, and SMAD4 with microsatellite stability and low tumor mutation burden." (PMID 41120769, 2025). "In approximately 40% of PDAC, mutations of the SMAD4 gene impair this tumor‐suppressive function, thereby promoting tumor progression." (PMID 40182139, 2025). "Recent preclinical models show that PSCC can become resistant to cisplatin when the tumor loses the PTEN tumor suppressor (especially on a SMAD4/APC-deficient background)." (PMID 41514559, 2025). "In CCA, SMAD4 is among the most frequently mutated genes and has been shown to curtail cell proliferation, tumor progression and drug resistance through TGF-β and Wnt/β-catenin signaling pathways." (PMID 39143229, 2025). "THBS1 also promotes tumor metastasis in post-dormancy stages of PDAC by converting latent TGF-β1 complexes to their active form through loss of the tumor suppressor Smad4 and upregulation of MMP-9 production." (PMID 40507347, 2025). "Loss of SMAD4 contributes to tumor progression by impairing cell differentiation and promoting epithelial–mesenchymal transition (EMT), a process associated with increased invasiveness and metastasis." (PMID 40072110, 2025). "An abnormality associated with SMAD loss, based on the tumor site, loss of SMAD4 was seen in the liver mass and common bile duct." (PMID 40487260, 2025). "Deletions in the chromosome 18q region are often linked to the loss of SMAD4, a tumor suppressor involved in TGF-β signaling." (PMID 40072110, 2025). "Loss of SMAD4 has been shown to increase intracellular reactive oxygen species (ROS) levels and autophagic flux following radiation, enhancing tumor cell resilience to oxidative stress." (PMID 40725389, 2025). "SMAD4 loss in KrasG12V PDAC differently altered the tumor microenvironment compared to KrasG12D PDAC, and the malignant compartment lacked JAK/STAT signaling dependency." (PMID 39841099, 2025). "Here, we show how SMAD4 loss in PDAC malignant cells shapes tumor biology differently in the presence of two distinct KRAS mutations." (PMID 39841099, 2025).
tumor (continued). "Of note, similar to the dichotomous effects of TGF-β-SF ligands in HCC, Smad4 displays a dichotomous behavior; while positively associated with tumor suppression at the initial stages of HCC, it becomes a tumor promoter at the late stages." (PMID 40260391, 2025). "Reduced Smad4 levels are associated with increased tumor aggressiveness, advanced stages, and poorer prognosis." (PMID 40507242, 2025). "Collectively, these results show that dissemination to the liver versus lungs favors distinct chromatin states in tumor cells, whereby certain TF activities are stably inherited and associated with opposite dependence on Smad4 inactivation." (PMID 40999053, 2025). "Inactivating mutations or deletions in SMAD4 (also known as DPC4), another key tumor suppressor gene, are observed in 30% to 60% of PDACs." (PMID 41228342, 2025). "TGF‐β signaling is well established to play a critical role in PDAC, as evidenced by the frequent mutations in SMAD4, a tumor suppressor gene encoding a transcription factor that is a central mediator of the TGF‐β pathway." (PMID 40739706, 2025). "Wildtype SMAD4 acts as a tumor suppressor, but SMAD4 mutations are commonly found in tumors and are associated with tumor progression and metastatic spread." (PMID 39335144, 2024). "This study explores how Smad4 deficiency affects pancreatic weight across genetic backgrounds and sexes, focusing on physiological impacts beyond its known role in tumor suppression." (PMID 39596873, 2024). "In cancers, the loss or inactivation of SMAD4 impairs the ability of TGF-β to suppress tumours, instead promoting cancer progression." (PMID 39589938, 2024). "The loss or functional impairment of the SMAD4 gene promotes tumor initiation and progression through multiple mechanisms." (PMID 39164192, 2024). "The impact of SMAD4 mutations varies among different tumor types, contributing differently to tumor initiation and progression." (PMID 38666907, 2024). "Loss or reduced expression of Smad4 is strongly associated with tumor progression, metastasis, and poor prognosis across these cancers." (PMID 39596873, 2024). "Loss-of-function mutation(s) in Smad4, a tumor suppressor, is(are) one of the critical drivers of colon cancers." (PMID 39366762, 2024). "This loss facilitates tumor progression, metastasis and angiogenesis through Smad4-independent pathways, contributing to the complexity of PDAC." (PMID 38666907, 2024). "BMS309403 effectively reversed the accelerated tumor growth caused by myeloid cell-specific Smad4 deletion." (PMID 39664586, 2024). "GSTO2 and MT1M functions have not been reported as factors in PCa progression, whereas loss of SMAD4 function has been shown to drive tumor growth and metastasis." (PMID 38751776, 2024). "As expected, the levels of SMAD4 were distinctly decreased, and the factors associated with stemness and metastasis were significantly elevated in tumor tissues obtained from LINC00909-OE mice." (PMID 38504385, 2024). "And, particularly notably, the combination of olaparib and radiotherapy specifically reduced tumor growth in SMAD4-deficient PDAC." (PMID 39528473, 2024). "MiR-210-3p is implicated in liver carcinogenesis and tumor angiogenesis through targets like SMAD4 and STAT6 and is driven by hypoxia-inducible factor 1α." (PMID 39456643, 2024). "Many studies showed that not only complete loss of SMAD4 is associated with tumor progression, but also decreased SMAD4 expression level is an important factor in adverse disease prognosis and resistance to chemotherapy 3-5." (PMID 39132157, 2024). "SMAD4 is thought to be a tumor suppressor with mutation or deletion of SMAD4 correlating with a worse survival rate for patients with PC." (PMID 39128718, 2024).